ITPK1 (inositol-tetrakisphosphate 1-kinase)
Description:
Kinase that can phosphorylate various inositol polyphosphate such as Ins(3,4,5,6)P4 or Ins(1,3,4)P3. Phosphorylates Ins(3,4,5,6)P4 at position 1 to form Ins(1,3,4,5,6)P5. This reaction is thought to have regulatory importance, since Ins(3,4,5,6)P4 is an inhibitor of plasma membrane Ca(2+)-activated Cl(-) channels, while Ins(1,3,4,5,6)P5 is not. Also phosphorylates Ins(1,3,4)P3 on O-5 and O-6 to form Ins(1,3,4,6)P4, an essential molecule in the hexakisphosphate (InsP6) pathway. Also acts as an inositol polyphosphate phosphatase that dephosphorylates Ins(1,3,4,5)P4 and Ins(1,3,4,6)P4 to Ins(1,3,4)P3, and Ins(1,3,4,5,6)P5 to Ins(3,4,5,6)P4. May also act as an isomerase that interconverts the inositol tetrakisphosphate isomers Ins(1,3,4,5)P4 and Ins(1,3,4,6)P4 in the presence of ADP and magnesium. Probably acts as the rate-limiting enzyme of the InsP6 pathway. Modifies TNF-induced apoptosis by interfering with the activation of TNFRSF1A-associated death domain. Plays an important role in MLKL-mediated necroptosis. Produces highly phosphorylated inositol phosphates such as inositolhexakisphosphate (InsP6) which bind to MLKL mediating the release of an N-terminal auto-inhibitory region leading to its activation. Essential for activated phospho-MLKL to oligomerize and localize to the cell membrane during necroptosis.
Synonyms: ITRPK1
Tractability: Small molecule: a structure with a bound ligand is known; it has a high-quality binding pocket. PROTAC: ubiquitination databases record sites on it; its protein half-life has been measured.
Target class: Enzyme
Gene: Protein-coding gene on chromosome 14 (92,936,914 to 93,116,458, reverse strand). Ensembl gene ENSG00000100605.
Subcellular location (Human Protein Atlas): Mitochondria
Pathways (Reactome):
Metabolism: Synthesis of IP3 and IP4 in the cytosol; Synthesis of pyrophosphates in the cytosol
Hemostasis: Factors involved in megakaryocyte development and platelet production
Gene Ontology:
Molecular function: inositol-1,3,4,5-tetrakisphosphate 6-kinase activity; inositol-1,3,4-trisphosphate 5-kinase activity; inositol-1,3,4-trisphosphate 6-kinase activity; inositol-3,4,5,6-tetrakisphosphate 1-kinase activity; inositol-3,4,6-trisphosphate 1-kinase activity; protein binding; catalytic activity; ATP binding; magnesium ion binding; metal ion binding
Biological process: necroptotic process; blood coagulation; signal transduction; inositol trisphosphate metabolic process
Cellular component: cytosol; apical plasma membrane
Genetic constraint (gnomAD): Loss-of-function variants: 16 observed, 34.22 expected, observed/expected ratio (o/e) 0.47, 90% interval 0.32 to 0.71. The upper end of that interval is the gene's LOEUF score, 0.71, which puts it in group 2 of 6, group 1 being the genes least tolerant of losing a copy. Missense variants: 451 observed, 519.91 expected, observed/expected ratio (o/e) 0.87, 90% interval 0.8 to 0.94. Synonymous variants: 249 observed, 235.33 expected, observed/expected ratio (o/e) 1.06, 90% interval 0.95 to 1.17.
Homologues: Orthologues: chimpanzee ITPK1 (99% identical), pig ITPK1 (94% identical), rat Itpk1 (94% identical), mouse Itpk1 (94% identical), guinea pig ITPK1 (93% identical), macaque ITPK1 (91% identical), rabbit ITPK1 (91% identical), tropical clawed frog itpk1 (74% identical), zebrafish itpk1b (68% identical), zebrafish itpk1a (63% identical).
Diseases named in the same sentence as ITPK1 in open-access papers:
ITPK1 is named in the same sentence as 21 diseases in open-access papers, as found by Europe PMC text mining. Sharing a sentence is not in itself a finding about the gene and the disease. The quoted sentences say what the papers report.
breast carcinoma (5 papers, 2019 to 2023). "Inositol-tetrakisphosphate 1-kinase variant ITPK1:27 was found over expressed in breast cancer but was also found downregulated in the AKT1 silenced sample compared to control (siNoN)." (PMID 35892586, 2022). "The findings of the present study indicate that increased expression of MRAS is linked to decreased expression of ITPK1 in breast cancer, which might lead to underproduction of inositol phosphate 6 (IP6)." (PMID 36077026, 2022). "Considering this information, the possible oncogenic effect of MRAS can be expected to be suppressed by positive coexpression of ITPK1 and reversed in breast cancer." (PMID 36077026, 2022). "Except for the five genes ITPK1, RIPK3, STAT3, TNF, and FASLG, the remaining 62 genes showed significant differences in expression between breast cancer and normal breast samples." (PMID 36675706, 2022).
Headache (2 papers, 2022 to 2023). Cephalgia, or pain sensed in various parts of the head, not confined to the area of distribution of any nerve. "Among the identified novel loci throughout the headache and thyroid trait combinations, the strongest and most significant association was at chromosome 14, rs12883201 (pmeta = 4.55 × 10−10) for headache and fT4, located near ITPK1." (PMID 36672757, 2022). "Of the genes at these loci, six (FAF1, TMX2-CTNND1, AARSD1, PLCD3, ZNF652, and C20orf203; headache-TSH) and six (HMGB1P45, RPL30P1, ZNF462, TMX2-CTNND1, ITPK1, SECISBP2L; headache-fT4) were significant in our gene-based analysis (pFisher’s combined p-value < 2.09 × 10−6)." (PMID 36672757, 2022).
migraine (2 papers, 2022 to 2023). "ITPK1, THADA, and ZNF652 have also been reported to be GWS in the recent TSH GWAS implying that these genes are important in headache, migraine, and thyroid traits physiology." (PMID 36672757, 2022). "Interestingly, some of these loci mapped to genes including ITPK1, ZNF462, RPL30P1, ANKDD1B, THADA, ZNF652, and C20orf203 that have been reported as genome-wide significant in the most recent migraine GWAS." (PMID 36672757, 2022).
adenoma (1 paper, 2024). A neoplasm arising from the epithelium. "In the LNM-positive group compared to the control adenoma, there were significant increases in gene expression for CCL15, SSX1, and KRT5 genes, alongside significant decreases in HLA-E, ITPK1, ANXA1, and TXNIP genes across the head, proximal stalk, and distal stalk regions." (PMID 38256174, 2024).
anencephaly (1 paper, 2014). A rare neural tube defect during pregnancy, resulting in the absence of a large portion of the brain and skull in the fetus. "So we analyzed the association of the ITPK1 polymorphisms with NTD phenotypes (anencephaly, spina bifida)." (PMID 24465924, 2014).
cognitive decline (1 paper, 2022). "In follow-up work, the ROS/MAP group later explained the association between ITPK1 and cognitive decline to be mediated by microstructural changes in the brain." (PMID 36359320, 2022). "A recent proteomics study in human brain samples from the ROS/MAP dataset showed an association between levels of ITPK1 protein and cognitive decline." (PMID 36359320, 2022).
myocardial infarction (1 paper, 2019). Gross necrosis of the myocardium, as a result of interruption of the blood supply to the area, as in coronary thrombosis. "In addition, cg05284742 related to NO2 exposure is located in ITPK1; this gene contains rs2295394 (p value = 2.3E-16) associated with myocardial infarction in Asian populations." (PMID 30819252, 2019).
spina bifida (1 paper, 2014). A congenital neural tube defect in which vertebrae are not fully formed. "It is suggested that spina bifida is more susceptible to the polymorphism of ITPK1 in NTD-affected pregnancies." (PMID 24465924, 2014).
viral infection (1 paper, 2025). "As an important regulatory enzyme of the phosphatidylinositol signaling pathway, inositol-tetrakisphosphate 1-kinase (ITPK1) is crucial for the activation of viral infection-induced necroptosis." (PMID 39858052, 2025).
cancer (4 papers, 2015 to 2022). A tumor composed of atypical neoplastic, often pleomorphic cells that invade other tissues. "Splice variants related to four genes (DBNDD2, DAP, ITPK1, and ROGDI) previously reported upregulated in breast/other human cancers were found downregulated in AKT1 silenced samples compared to control (siNoN)." (PMID 35892586, 2022). "For example, GOLGA7, ITPK1, and NPRL3 were correlated with increased drug resistance of cancer cells to Dasatinib, Zoledronate, PF-06463922, Brigatinib, LDK-378, Vinorelbine, Carfilzomib, and Bortezomib, respectively." (PMID 34970268, 2021).
tumor (4 papers, 2015 to 2022). "GOLGA7, ITPK1, and ST6GALNAC4 genes had lower expression in tumor tissues than in healthy persons (p < 0.05) by means of Wilcoxon signed-rank test." (PMID 34970268, 2021).
neurodegenerative disease (1 paper, 2022). A disorder of the central nervous system characterized by gradual and progressive loss of neural tissue and neurologic function. "These include SNCA, SEPW1, ITPK1, and APBA2, which have all been previously implicated to relate to neurodegenerative diseases and/or cognitive functioning." (PMID 36359320, 2022).
ITPK1 also shares sentences with these, for which no sentence is quoted: glioma (2 papers); heart failure (2); systemic lupus erythematosus (2); Anxiety (1); depression (1); hypothyroidism (1); neural tube defect (1); Stroke (1); thyroid (1).